PHGDH (phosphoglycerate dehydrogenase)
Diseases named in the same sentence as PHGDH in open-access papers (continued):
Sharing a sentence is not in itself a finding about the gene and the disease.
breast carcinoma (continued). "Still, it was not until the later discovery of increased expression of the PHGDH gene in breast cancer and melanoma that researchers brought the PHGDH pathway into the light." (PMID 36803157, 2023). "The use of second-generation PHGDH inhibitors (PH-719 and PH-755) inhibits the growth of breast cancer and colon cancer cells in serine-limited environments and attenuates breast cancer brain metastasis." (PMID 37187454, 2023). "Amplification of the PHGDH gene was identified in several cancers including breast cancer and melanoma, leading to corresponding enzyme overexpression, and decreased PHGDH expression impaired flux into serine synthesis and cell proliferation." (PMID 37284309, 2023). "Because different models were used in these studies, it is likely that the role of PHGDH in breast cancer depends on the genetic background, cellular context, and microenvironment, which warrants further investigation." (PMID 37444501, 2023). "Acetylation of PHGDH at the Lys-58 site can prevent the interaction between RNF5 and PHGDH, thereby stabilizing PHGDH and promoting the proliferation of breast cancer cells." (PMID 37190313, 2023). "Studies have demonstrated that PHGDH is upregulated in a variety of cancers, like colorectal cancer, breast cancer, and gastric cancer, regarding cancer initiation, proliferation, differentiation, and metastases." (PMID 37387559, 2023). "In an in vivo shRNA screen using the MCF10CDIS.COM human breast cancer cell line, PHGDH was identified as a key player in breast tumorigenesis." (PMID 37444501, 2023). "In a 4T1 mouse mammary tumor model, both circulating tumor cells and early metastatic lesions were enriched in PHGDHlow cells, and knockdown of PHGDH promoted lung metastasis." (PMID 37444501, 2023). "Studies have indicated that suppression of PHGDH inhibits cell proliferation in breast cancer in the presence of exogenous serine." (PMID 36291844, 2022). "Phosphoglycerate dehydrogenase (PHGDH) is overexpressed in breast cancer and melanoma, directing the metabolism toward the serine biosynthesis pathway." (PMID 35935878, 2022). "One breast cancer study found that PHGDH and PSPH are highly expressed in in vitro TNBC, and these, along with SHMT-1, are also elevated in stromal TNBC tumors." (PMID 35565690, 2022). "It is reported that PHGDH is overexpressed in a subset of breast cancer, cervical cancer, and melanoma." (PMID 35204409, 2022). "Another study found that brain metastatic breast cancer cells upregulate de novo serine when deprived of the exogenous alternative, and PHGDH suppression reduces brain metastases of NCSLC and TNBC in vivo." (PMID 35565690, 2022). "Proteomic profiling in breast cancers has identified PHGDH as one of the proteins expressed specifically in triple-negative breast cancers, which often have a basal-like phenotype defined by positivity for EGFR and CK5." (PMID 35204409, 2022). "PHGDH is an indispensable factor in breast cancer pulmonary metastasis, which elevates the mTOR complex 1 (mTORC1) signaling pathway and defines sensitivity to rapamycin in tumor metastases." (PMID 36699468, 2022). "Upregulation of PHGDH has been observed in many cancers, including melanoma, breast cancer, leukemia and colorectal cancer." (PMID 36072341, 2022). "Initial efforts of targeting serine metabolism in breast cancer were focused on “gain-of-function” cases in which the amplification of PHGDH leads to elevated rates of serine biosynthesis in basal tumors." (PMID 35045283, 2022). "In turn, phosphoglycerate dehydrogenase (PHGDH), which is a crucial enzyme in the serine synthesis pathway, is greatly upregulated in breast cancer cells." (PMID 35646057, 2022). "Previously, breast cancer cells have shown to promote serine biosynthetic flux though the activation of PHGDH that catalyzes the first step of serine biosynthesis." (PMID 35122791, 2022).
breast carcinoma (continued). "The de novo serine/glycine biosynthesis pathway gained interest after the discovery of PHGDH amplification in melanoma and breast cancer, which was correlated with a worse prognosis." (PMID 33801846, 2021). "Here, using metabolomic profiling followed by mechanistic verification, we show that metformin suppresses the growth of the MCF-7 estrogen receptor-positive breast cancer cell line through the inhibition of 2-HG production by PHGDH." (PMID 34436421, 2021). "This perspective article will discuss the current status of research into small molecular inhibitors against PHGDH in colorectal cancer, breast cancer, and Ewing’s sarcoma." (PMID 33931592, 2021). "Overall, our study suggests a possible mechanistic linkage among metformin’s effect on cancer cells, PHGDH’s roles, and 2-HG production in ER-positive breast cancer cells." (PMID 34436421, 2021). "This is also consistent with the elevated 2-HG level in breast carcinoma cell lines and its possible usage as a predictive marker for malignancy, and PHGDH’s roles in tumor formation and breast cancer metastasis." (PMID 34436421, 2021). "Compared with breast cancer cells with weak bone metastasis activity, the expression of de novo serine synthesis enzymes, including PHGDH, PSAT1, and PSPH, is increased in breast cancer cells with high bone metastasis activity." (PMID 33926551, 2021). "Hypoxia-inducible factors (HIF) has reported to regulate expression of genes encoding PHGDH and five downstream enzymes including MTHFD2 and SHMT2 in the serine synthesis pathway and mitochondrial one-carbon cycle in breast cancer stem cells." (PMID 33468252, 2021). "We expanded PHGDH’s roles from producing 2-HG in triple-negative breast cancer cells, to the regulation of metformin’s growth inhibitory effect on ER-positive breast cancer cells." (PMID 34436421, 2021). "At present, the expression of PHGDH has been found increased in multiple types of cancers, including breast cancer, cervical cancer, glioma, melanoma, pancreatic cancer, and colon cancer." (PMID 33763366, 2021). "PKUMDL-WQ-2101 and PKUMDL-WQ-2201, which are allosteric PHGDH inhibitors, show an antitumor activity in PHGDH-amplified breast cancer cell lines (MDA-MB-468 and HCC70)." (PMID 34552932, 2021). "PHGDH is overexpressed in some types of cancer, such as non-small cell lung, cervical, colorectal, and breast cancers." (PMID 34071836, 2021). "For breast cancer, PHGDH has been shown to be overexpressed mostly in estrogen receptor-negative subtypes, including triple-negative subtypes." (PMID 34436421, 2021). "Recently, PHGDH was shown to be a major determinant of brain metastasis in multiple human cancer types and preclinical models of breast cancer and melanoma." (PMID 33401771, 2021). "Regarding bone metastasis, breast cancer cells show increased serine biosynthesis through the expression of phosphoglycerate dehydrogenase (PHGDH), phosphoserine aminotransferase, (PSAT1), and phosphoserine phosphatase (PSPH)." (PMID 33915900, 2021). "In breast cancer, SF3B1 mutations induce missplicing‐associated downregulation of the serine synthesis pathway enzyme PHGDH and decrease mitochondrial respiration." (PMID 33932092, 2021). "Analysis using the cBioPortal TCGA Pan-Cancer Atlas shows PHGDH amplification in approximately 2.2% of breast cancers." (PMID 34552932, 2021). "In vivo studies have also shown that increased PHGDH expression promotes tumor progression in mouse models of melanoma and breast cancer." (PMID 33801846, 2021). "An NAD-competitive PHGDH inhibitor, 15 fragments, reduces cell proliferation in PHGDH-amplified breast cancer cell line (MDA-MB-468)." (PMID 34552932, 2021). "In PHGDH-overexpressing breast cancer cells, the synthetic serine pathway not only produces serine but also generate glutamate-derived α-KG." (PMID 32296646, 2020).
breast carcinoma (continued). "Nearly half of α-KG influx into the TCA cycle is from the synthetic serine pathway, which is crucial for proliferation of PHGDH-amplified breast cancer cells." (PMID 32296646, 2020). "3-phosphoglycerate dehydrogenase (PHGDH) is the rate-limiting enzyme of de novo serine biosynthesis and is highly expressed in a variety of cancers, including breast cancer, melanoma, and Ewing’s sarcoma." (PMID 33511334, 2020). "PKUMDL-WQ- 2101 and PKUMDL-WQ-2201 were confirmed to specifically bind to PHGDH in PHGDH-amplified breast cancer cells with EC50 values less than 10 μM in serine-replete media." (PMID 32226297, 2020). "Phosphoglycerate dehydrogenase (PHGDH) is a crucial enzyme for serine synthesis, and the expression levels of PHGDH are significantly increased in breast cancer cells." (PMID 33077737, 2020). "Increased copy number of the Phgdh gene in mice led to increased PHGDH expression and promoted the development of melanoma and breast cancer cells." (PMID 32477466, 2020). "Small molecule PHGDH inhibitors can abrogate the serine synthetic pathway and decrease proliferation of PHGDH-overexpressing breast cancer cells in vitro and in vivo." (PMID 32296646, 2020). "It inhibits PHGDH oligomerization and has a significant inhibitory effect in melanoma and breast cancer cell lines with a high PHGDH, especially when extracellular serine is absent." (PMID 32824193, 2020). "This mutation had been previously shown to decrease NCT-503 binding to PHGDH and restore serine flux in breast cancer cells." (PMID 32138178, 2020). "For example, phosphoglycerate dehydrogenase (PHGDH) is frequently amplified in melanoma and breast cancer; the PHGDH enzyme is critical for serine biosynthesis and regulates the methyl donor methionine thus modulating the cell methylome and epigenetic state." (PMID 33339101, 2020). "PHGDH amplified breast cancer cell lines are dependent on de novo serine synthesis for their proliferation." (PMID 31186416, 2019). "The inhibitors of PHGDH reduce the production of glucose-derived serine and suppress the growth of PHGDH-dependent breast cancers in culture and in orthotopic xenograft tumors and concomitantly reduce the nucleotide synthesis." (PMID 30744688, 2019). "The enzyme has been recognized as a potential therapeutic target for NAD-competitive inhibitors in PHGDH-amplified breast cancer." (PMID 30857125, 2019). "PHGDH overexpression has been found in breast cancer samples, especially in those with the estrogen receptor-negative (ER: negative) phenotype." (PMID 31861486, 2019). "Recently, HIF-dependent expression of the serine synthesis pathway enzyme phosphoglycerate dehydrogenase was shown to be required for breast cancer metastasis." (PMID 30674873, 2019). "Knockdown caused reduced proliferation in the PHGDH-amplified cell line MDA-MB-468, whereas breast cancer cells with low PHGDH expression or with elevated PHGDH expression in the absence of genomic amplification were not affected." (PMID 29568346, 2018). "Phosphoglycerate dehydrogenase (PHGDH), the enzyme which catalyzes the first step of the serine biosynthesis pathway, has been shown to be genomically amplified in many breast cancers and melanomas." (PMID 30250195, 2018). "Of the cell lines investigated, those derived from breast cancer and melanoma demonstrated the highest levels of PHGDH expression." (PMID 29568346, 2018). "The observed higher expression of PHGDH in breast cancer and melanoma cells is in line with previous observations regarding elevation of PHGDH in these cell types and their potential dependence on PHGDH-mediated supply of oncometabolites." (PMID 29568346, 2018). "We have used siRNA-mediated suppression of PHGDH expression to show that PHGDH is a potential therapeutic target in PHGDH-amplified breast cancer." (PMID 29568346, 2018).
breast carcinoma (continued). "Consistent with the genetic data, knockdown of PHGDH in melanoma and breast cancer cell lines containing a PHGDH amplification, resulted in decreased cell viability." (PMID 29568346, 2018). "In our study we confirmed that knockdown of PHGDH resulted in significant growth reduction in the PHGDH-amplified breast cancer cell line MDA-MB-468." (PMID 29568346, 2018). "PHGDH, the enzyme that catalyzes the first reaction in the de novo serine synthesis pathway from 3PG, is overexpressed in breast carcinomas and melanomas." (PMID 29805774, 2018). "For example, phosphoglycerate dehydrogenase (PHGDH), the first and rate-limiting enzyme in glucose-derived serine biosynthesis, is upregulated in breast cancer and melanoma due to amplification of its gene copy." (PMID 30283496, 2018). "We also analyzed the correlation between TAZ or YAP1 mRNA expression and LKB1 mRNA levels as well as the relevance between TAZ or YAP1 mRNA expression and PHGDH mRNA levels in the breast cancer dataset from The Cancer Genome Atlas." (PMID 28931725, 2017). "In breast cancer cells, PHGDH knockdown and consequent impairment of the mitochondrial folate cycle led to a decrease in NADPH level of ~50 and ~30% in MDA-MB-231 and in MCF7 cell lines, respectively, thus confirming the prediction by Fan and colleagues." (PMID 28649560, 2017). "PHGDH-ablated breast cancer cells are sensitized to ROS-inducing chemotherapy and, despite being tumorigenic, do not generate lung metastases in vivo, due to loss of the cancer stem cell population." (PMID 28649560, 2017). "PHGDH, the first enzyme of the de novo serine synthesis pathway, was found to be amplified in both breast cancer and melanoma." (PMID 29137367, 2017). "Recent work highlighted the importance of human PHGDH in certain cancer types with amplified PHGDH, e.g. breast cancer and melanoma, with PHGDH knockdown resulting in reduced cancer cell growth." (PMID 29262655, 2017). "Reducing PHGDH expression impaired the cancer cell proliferation, whereas overexpression of PHGDH in human breast cancer contributed to carcinogenesis by facilitating glycolysis to SSP." (PMID 27356757, 2016). "Recent evidence has shown that PHGDH is amplified and over-expressed in certain types of melanomas and breast cancer and plays a key role in cancer metabolism by influencing proliferation and metastases." (PMID 26821323, 2016). "PHGDH copy number gain has been observed with the highest frequency in melanoma and breast cancer, and PHGDH-amplified cell lines are dependent on enzyme expression to proliferate in culture." (PMID 25926973, 2015). "According to previous reports, these enzymes are highly expressed in several human tumors: PHGDH in breast cancer and melanoma and GLDC in lung cancer." (PMID 24979213, 2014). "We used western blotting and immunohistochemistry to examine five serine-/glycine-metabolism–associated proteins (PHGDH, PSAT, PSPH, SHMT, and GLDC) in six breast cancer cell lines and 709 breast cancer cases using tissue microarray (TMA)." (PMID 24979213, 2014). "As with tumorigenic breast cancer, melanoma, and astrocytoma cells, PHGDH was more strongly expressed in cervical cancer relative to normal cervical epithelium (72 versus 29%, P < 0.05)." (PMID 25574168, 2014). "From our analysis SHMT-2, even more than PHGDH, appears to be highly clinical relevant for breast cancer." (PMID 25436979, 2014). "In breast cancer, elevated PHGDH levels are more frequently found in estrogen receptor-negative and basal-like tumors." (PMID 23229761, 2013). "As a key enzyme in serine de novo synthesis, inhibition of PHGDH inhibits tumor proliferation and reverses the malignant phenotype in breast cancer and menaloma." (PMID 23229761, 2013). "We observe that PHGDH knockdown decreases the production of serine and glycine and impairs glucose metabolism in ER− breast cancer cell lines with overexpression of PHGDH and inhibits the proliferation of these breast cancer cells in vitro." (PMID 24318446, 2013).
breast carcinoma (continued). "Depletion of PHGDH strongly inhibited the proliferation of a panel of breast cancer cells with amplified or overexpressed PHGDH." (PMID 23229761, 2013). "The effect of PHGDH knockdown was observed among 8 breast cancer cell lines and 1 normal breast cell line." (PMID 24318446, 2013). "Recent evidence has shown that PHGDH is amplified in human breast cancer and melanoma and plays a key role in cancer metabolism." (PMID 23229761, 2013). "Evidence has shown that PHGDH is amplified or overexpressed in a subset of melanoma and breast cancers." (PMID 23229761, 2013). "As PHGDH amplification is associated with significant protein overexpression in primary human breast cancer and melanoma, we next assessed PHGDH copy number in these breast cancer cell lines." (PMID 24318446, 2013). "Reducing PHGDH expression impairs the proliferation in amplified cell, whereas overexpression of PHGDH in human breast cancer contributed to carcinogenesis by facilitating glycolytic pathway to serine biosynthetic pathway." (PMID 24138801, 2013). "Our findings, as well as those from other groups, suggest that PHGDH is overexpressed in a subset of ER− breast cancer cell lines." (PMID 24318446, 2013). "Here, we show that PHGDH is overexpressed in ER-negative human breast cancer cells and PHGDH knockdown impairs the proliferation of those cells in vitro." (PMID 24318446, 2013). "A recent study of breast cancer further uncovered alterations in glucose metabolism mediated by phosphoglycerate dehydrogenase (PHGDH) enzyme, whose expression was found to be associated with poor prognosis." (PMID 24957377, 2012). "PHGDH up-regulation, which was observed in a majority of the breast cancer cell lines we examined, increases glucose-derived serine production." (PMID 21437235, 2011). "Similarly, the NAD+ salvage pathway is essential for sustaining PHGDH activity in breast cancers, where NAMPT-mediated NAD+ regeneration promotes serine production and tumor growth." (PMID 41486146, 2026). "When PHGDH is highly expressed in primary breast cancer, it can enhance tumor cell proliferation through its catalytic function; conversely, when expression is heterogeneous or low, it promotes integrin αvβ3 sialylation, thereby enhancing tumor metastasis and invasiveness." (PMID 39973065, 2025). "Additionally, silencing PHGDH can reverse tamoxifen resistance in estrogen receptor-positive breast cancer cells in vitro." (PMID 39973065, 2025). "In breast cancer tissues, PHGDH expression is significantly up‐regulated." (PMID 39778006, 2025). "In addition, genes encoding metabolic enzymes such as phosphoglycerate dehydrogenase (PHGDH) can be amplified, leading to increased biosynthesis of serine, which is essential for proliferation of breast cancer and melanomas." (PMID 40550880, 2025). "Inhibiting PHGDH, specifically disrupts these processes, impairing cell proliferation and metastatic potential, making it a promising therapeutic target for E-cadherin+ breast cancers." (PMID 39973065, 2025). "This limited serine supply led to PHGDH dependency in brain metastases of breast cancer." (PMID 38515202, 2024). "In addition, patients with brain metastasis of breast cancer were found to have higher PHGDH expression than did patients with extracranial metastases, including lung, liver, and ovarian metastases, of breast cancer." (PMID 38945960, 2024). "In addition, the IHC results showed that ASS1 was negatively associated with breast cancer recurrence, whereas PHGDH was positively associated with breast cancer recurrence, and ASS1 was negatively associated with PHGDH in TNBC patient tissue." (PMID 38710705, 2024). "Many studies have confirmed the dysregulation of serine uptake or biosynthesis in tumour cells, as well as abnormal PHGDH expression, in different tumours, including lymphoma, multiple myeloma, glioma, hepatocellular carcinoma, melanoma, colon cancer, breast cancer, and others 32-38." (PMID 38577610, 2024).